RN7SL164P (RNA, 7SL, cytoplasmic 164, pseudogene)
Gene: Miscellaneous RNA gene on chromosome 13 (96,169,545 to 96,169,847, forward strand). Ensembl gene ENSG00000242614.
Homologues: Orthologues: chimpanzee Metazoa_SRP (99% identical), macaque Metazoa_SRP (87% identical). Paralogues in human: RN7SL2 (83% identical), RN7SL1 (82% identical), RN7SL3 (80% identical), RN7SL126P (79% identical), RN7SL357P (79% identical), RN7SL326P (79% identical), RN7SL45P (79% identical), RN7SL296P (78% identical), RN7SL786P (78% identical), RN7SL660P (78% identical), RN7SL444P (78% identical), RN7SL44P (77% identical), and 700 more.